HMGB1 (high mobility group box 1)
Diseases named in the same sentence as HMGB1 in open-access papers (continued):
Sharing a sentence is not in itself a finding about the gene and the disease.
atopic dermatitis (9 papers, 2016 to 2025). "For example, glycyrrhizin (an extract of licorice root) diminished atopic dermatitis symptoms, and inhibitory effects of that compound were also observable in the mast cell line P815, where glycyrrhizin caused the inhibition of HMGB1-RAGE interaction." (PMID 33158024, 2020). "NF-κB and the subsequent production of IL-6 were also shown to be downregulated in mice with TPA-induced atopic dermatitis, when they were treated with Glycyrrhiza glabra, a direct inhibitor of HMGB1, one of the main ligands of RAGE." (PMID 33435332, 2021). "Among children with aAEDS and naAEDS, those with severe score atopic dermatitis values had increased levels of HMGB1, indicating that HMGB1 was a biomarker of the severity of AEDS." (PMID 33140586, 2021). "Three of these studies focused mostly on HMGB1, in diseases such as atopic dermatitis, cholesteatoma, and lichen planus (all of them being chronic diseases)." (PMID 33435332, 2021). "Recently, resveratrol was shown to effectively reduce the expression of HMGB1, RAGE, and various cytokines, including TNF-α and IL-4, in inflamed skin caused by atopic dermatitis." (PMID 26950148, 2016). "A recent study has shown that, in animal models of atopic dermatitis, atopic dermatitis-like symptoms were further improved by inhibiting HMGB1 expression in mast cells, preventing NF-κB nuclear translocation, and reducing the release of cytokines such as TNF-α and IL-1β." (PMID 34007295, 2021). "Of interest, atopic features (such as food allergy and atopic dermatitis) represent key manifestations present in the majority of patients with the 13q12.3 microdeletion syndrome, which could help establishing clinical diagnosis and facilitate gene dosage ontology studies of the key player HMGB1." (PMID 39635340, 2024). "Also, the natural antioxidant quercetin inhibited atopic dermatitis by diminishing the HMGB1/RAGE/NFκB signaling pathway and resveratrol treatment diminished the skin inflammation (and the number of infiltrating MCs), in a murine model of dust mite-induced atopic dermatitis." (PMID 33158024, 2020).
autoimmune myocarditis (9 papers, 2014 to 2022). Autoimmune myocarditis is an autoimmune disease that affects the heart. "Systemic, as well as cardiac, HMGB1 levels are increased in mice with troponin-induced experimental autoimmune myocarditis and m2G7-based therapy reduced the cardiac inflammation and HMGB1 expression." (PMID 32265930, 2020). "Activation of the HMGB1/RAGE/NF-κB signaling pathway has been reported to be involved in regulating neurite outgrowth, HMGB1-mediated chemotaxis, autoimmune myocarditis and inflammatory cardiomyopathy." (PMID 31165005, 2019). "(2016) using autoimmune myocarditis model mice, recently demonstrated that HMGB1 facilitated macrophage polarization toward an M1-like phenotype and that this process was dependent on the TLR-4-PI3Kγ-Erk1/2 pathway." (PMID 29847178, 2018). "In mice, silencing of HMGB1 mitigates experimental autoimmune myocarditis." (PMID 33925132, 2021). "All-thiol or disulphide HMGB1 can expand group 3 innate lymphoid cells (ILC3), promoting IL-22 release and attenuating experimental autoimmune myocarditis." (PMID 33925132, 2021). "Studies have also shown that blocking of high-mobility group box 1 (HMGB1), a proinflammatory mediator by glycyrrhizin (GLC) and knocking out of RAGE suppressed inflammation in the heart in an experimental autoimmune myocarditis mice model." (PMID 33924458, 2021).
chronic rhinosinusitis (9 papers, 2015 to 2025). Chronic form of sinusitis. "Given the recent interest in HMGB1 with respect to the pathogenesis of eosinophil-associated disorders, including asthmatic inflammation and chronic rhinosinusitis, we have explored the role of this mediator and in promoting eosinophil activation." (PMID 25774667, 2015). "Similarly, HMGB1 has been implicated in the pathogenesis of chronic rhinosinusitis, an asthma co-morbidity characterized by eosinophils in nasal polyps and in mucous drainage." (PMID 25774667, 2015). "Our previous study demonstrated the expression of RAGE and HMGB1 in epithelial cells of sinonasal mucosa samples obtained from patients with chronic rhinosinusitis or in epithelial cells of middle ear cholesteatoma." (PMID 33776579, 2021). "HMGB1 expression has been observed by us in normal intestinal mucosa, in chronic rhinosinusitis, and in tumors rich in inflammatory infiltrates such as HNSCC (data not shown)." (PMID 25385222, 2015). "Patients with severe symptoms of chronic sinusitis have high HMGB1 serum levels." (PMID 34445093, 2021).
colon adenocarcinoma (9 papers, 2013 to 2023). "In this study, we investigated whether cyto-HMGB1 is associated with survival outcomes in patients with locally advanced colon adenocarcinoma (COAD) who received adjuvant chemotherapy." (PMID 37945630, 2023). "Exogenous recombinant HMGB1 also induced ER stress in CT26 cells (the murine colon adenocarcinoma cell line), while glycyrrhizin, an HMGB1 inhibitor, decreased ER stress." (PMID 33238880, 2020). "Human colon adenocarcinoma cell line, HT29, human epithelial colorectal adenocarcinoma, Caco2, and murine macrophage cell line, RAW 264.7, were cultured to investigate the effect of DPG on the secretion of HMGB1." (PMID 23840500, 2013). "To study the expression of HMGB1 redox isoforms in tumors and cachectic muscles, we employed two well-established mouse models of cancer cachexia: C57BL/6 and BalB/C mice injected subcutaneously with Lewis Lung Carcinoma (LLC) cells and colon adenocarcinoma C26 cells, respectively." (PMID 32670275, 2020).
hemorrhage (9 papers, 2011 to 2026). Loss of blood from the vascular compartment to the exterior or into nonvascular body space as a result of rupture or severance of the blood vessels. "On the other hand, in cases of isolated hemorrhage, the HMGB1 kinetics are much faster, with a plasmatic peak as early as 24 h in murine models of blood loss." (PMID 36726379, 2022). "Concerning the therapeutic time window of anti-HMGB1 mAb, 3–6 h after the start of insult was observed in rat hemorrhage and trauma." (PMID 33321691, 2020). "In accordance, anti-HMGB1 was previously shown to inhibit IL-1β release after airway endotoxin exposure and in pulmonary injury induced by hemorrhage." (PMID 24342460, 2013). "In terms of kinetics, the pulmonary level of HMGB1 increases from the fourth hour post-hemorrhage, when the plasma level has not yet increased." (PMID 36726379, 2022). "Mean HMGB1 levels in PDR patients with hemorrhage were significantly higher than those in PDR patients without hemorrhage and nondiabetic patients (p=0.0111)." (PMID 21850157, 2011). "Post-ANOVA pairwise comparisons of means highlighted that for HMGB1 the mean levels were significantly higher for PDR patients with hemorrhage than for PDR patients without hemorrhage (Z=2.82)." (PMID 21850157, 2011). "In addition, we demonstrated that HMGB1 levels in vitreous samples of PDR patients with hemorrhage were significantly higher than in PDR patients without hemorrhage." (PMID 21850157, 2011). "When patients with PDR were divided into those with or without hemorrhage, the mean levels of inflammatory biomarkers differed significantly between PDR patients with hemorrhage, PDR patients without hemorrhage, and nondiabetic patients for HMGB1 (p=0.0111) and sICAM-1 (p<0.001) but not for MCP-1." (PMID 21850157, 2011).
intracerebral hemorrhage (9 papers, 2012 to 2024). A cerebrovascular disorder characterized by bleeding into one or both cerebral hemispheres including the basal ganglia and the cerebral cortex. "HMGB1 is released from neurons in situations associated with neuroinflammation such as ischemic injury, traumatic injury, intracerebral hemorrhage, and spinal cord injury." (PMID 32917219, 2020). "In a rat model of intracerebral hemorrhage, miR-129-5p has been shown to be associated with the inhibition of revascularization and angiogenesis by suppressing HMGB1 and RAGE signaling." (PMID 29061187, 2017). "Further, HMGB1 promotes neurogenesis after intracerebral hemorrhage (ICH) in a RAGE-dependent manner." (PMID 36232519, 2022). "High mobility group box-1 (HMGB1) is released from neurons during ischemic injury, traumatic injury, intracerebral hemorrhage, and spinal cord injury." (PMID 32155899, 2020). "Potential neuroprotective effects of HMGB1 has been reported in few studies where anti-HMGB1 mAb prevented intracerebral hemorrhage (ICH)-induced brain injury." (PMID 30271319, 2018). "Consistent with this idea, findings from studies on repair mechanisms following intracerebral hemorrhage suggest a role of HMGB1 in neurogenesis." (PMID 23621913, 2013).
necrotizing enterocolitis (9 papers, 2021 to 2026). Necrotizing enterocolitis (NEC) is a devastating disease that affects mostly the intestine of premature infants. "The polymorphisms in the high mobility group box 1 protein (HMGB1) have been related to the necrotizing enterocolitis predisposition, as well as to survival." (PMID 40002629, 2025). "Intestinal HMGB1 levels were related to the severity of enteric infections in GN piglets, and its increased fecal levels were detected in newborn infants with necrotizing enterocolitis." (PMID 41474380, 2026). "Neonatal mouse models of necrotizing enterocolitis exhibited reduced levels of HMGB1, TLR4, and inflammatory cytokines after butyrate pretreatment." (PMID 38709282, 2024). "Inhibition of HMGB1 was found to improve intestinal inflammation in necrotizing enterocolitis by inhibiting NLR pyrin domain containing 3 via the TLR4 and NF-κB signaling pathways." (PMID 35335612, 2022). "This study aims to investigate clinical significance of HMGB1 in neonatal patients with necrotizing enterocolitis (NEC)." (PMID 34418984, 2021). "Inhibiting HMGB1 could improve intestinal inflammation in necrotizing enterocolitis by inhibiting NLRP3 via the TLR4 signalling pathway." (PMID 35197507, 2022). "To determine the role of sodium butyrate in intestinal inflammation via regulation of high-mobility group box-1 (HMGB1), we analyzed the potential mechanism in necrotizing enterocolitis (NEC) in a neonatal mouse model." (PMID 34675753, 2021). "In necrotizing enterocolitis (NEC) models, upregulated HMGB1 and NLRP3 expression exacerbate intestinal inflammation." (PMID 41354099, 2025).
nephritis (9 papers, 2012 to 2024). Inflammation of renal tissue. "Extracellular HMGB1 has been reported to increase macrophage inflammation and is highly correlated with histopathological features of renal injury in active nephritis via the TLR4/MyD88/NF-κB/p65 signaling pathway in LN." (PMID 37872565, 2023). "In SLE patients, NETs are a source of extracellular HMGB1, which correlates with clinical and histopathological features of active nephritis." (PMID 33925132, 2021). "Nonetheless, the presence of granulomatous manifestations in AAV patients did not seem to influence HMGB1 levels in AAV patients with simultaneously active nephritis, indicating that HMGB1 levels were mostly influenced by renal involvement." (PMID 24007972, 2013). "Since a certain number of patients will develop nephritis within the clinical course of IgAV, measuring the concentration of HMGB1 in the urine may be a useful tool in evaluating IgAV patients with nephritis and in making therapeutic approaches." (PMID 38673968, 2024). "The effects of gastrodin against carbon tetrachloride-induced kidney inflammation and fibrosis in mice via the AMPK/Nrf2/HMGB1 pathway have also been reported." (PMID 36733505, 2023). "Urinary HMGB1 was significantly higher in IgAV patients with nephritis compared to those without during the follow-up interval." (PMID 38673968, 2024). "We observed that AAV patients with renal involvement presented similar HMGB1 levels in comparison with HC while AAV patients without active nephritis had significantly higher HMGB1 levels than HC." (PMID 24007972, 2013). "Concentrations of HMGB1 in urine were higher in IgAV patients with nephritis compared to patients without nephritis in the follow-up period and showed positive correlations with the findings of erythrocyturia in urine tests, uACR and with the outcome of nephritis." (PMID 38673968, 2024). "In addition, there is one in vivo study in juvenile SLE patients that has shown a correlation of HMGB1 with the disease activity regardless of nephritis presence." (PMID 25516724, 2014). "In addition, there is one in vivo study in cSLE patients that has shown a correlation of HMGB1 with the disease activity regardless of the presence of nephritis." (PMID 25516724, 2014).
oral squamous cell carcinoma (9 papers, 2016 to 2025). "Similarly, in patients with oral squamous cell carcinoma, another HMGB1 polymorphism at the SNP rs3742305 has been associated with tumor progression and recurrence-free survival." (PMID 27116470, 2016).
papillary thyroid carcinoma (9 papers, 2013 to 2024). "HMGB1 increases the expression of miR-221 and miR-222 in primary cultures of excised papillary lesions and in an established papillary cancer cell line and overexpression of miR-222 and miR-221 caused by HMGB1 increases growth and motility in papillary thyroid cancer cells." (PMID 24575418, 2013). "In papillary thyroid carcinoma, let-7e inhibits migration and invasion through the downregulation of HMGB1." (PMID 33066614, 2020).
renal cell carcinoma (9 papers, 2017 to 2025). "In renal cell carcinoma, overexpression of HMGB1 is always closely associated with the malignancy of the tumor." (PMID 40969278, 2025). "Research findings indicate that HMGB1 may serve as both a diagnostic marker and treatment focus for renal cell carcinoma." (PMID 40969278, 2025). "In a clinicopathological analysis including 80 patients with renal cell carcinoma, elevated HMGB1 levels were significantly associated with unfavorable clinical outcomes, and this manifestation appeared to be achieved by affecting the receptor product of glycosylation endpoints(RAGE)." (PMID 40969278, 2025). "HMGB1/RAGE promotes renal cell carcinoma proliferation and invasion by inducing the expression of vascular endothelial growth factor (VEGF), and at the same time promotes renal cell carcinoma cell autophagy to enhance drug resistance." (PMID 40969278, 2025). "Knocking down HMGB1 in renal cell carcinoma significantly inhibits the expression of RAGE, as well as the expression of autophagy proteins LC3II and Beclin1." (PMID 38529373, 2024). "In renal cell carcinoma cell lines, reducing the expression of HMGB1 and RAGE significantly decreases the expression of vascular endothelial growth factors (VEGF) and its receptor VEGFR2." (PMID 38529373, 2024). "Our data support the future evaluation of HMGB1 as a predictive biomarker for bevacizumab sensitivity in patients with renal cell carcinoma." (PMID 30123419, 2018). "Therefore, we can inhibit angiogenesis and metastasis of renal cell carcinoma by targeting HMGB1 and use it in combination with other renal cell carcinoma therapies to prolong patient survival." (PMID 40969278, 2025). "Therefore, an in-depth understanding of the mechanisms of renal cell carcinoma occurrence, progression, and treatment has led to the proposal that targeting HMGB1 has significant benefits for patients with renal cell carcinoma." (PMID 40969278, 2025). "The HMGB1/RAGE axis regulates angiogenesis in renal cell carcinoma." (PMID 38529373, 2024). "In addition, HMGB1 was highly expressed in renal cell carcinoma, and the expression level showed a positive correlation with cancer bearing, metastasis and clinical staging and grading." (PMID 33191617, 2021). "However, the present study showed that by increasing the immunosuppression of MDSCs, HMGB1 successfully promoted the proliferation and development of renal cell carcinoma cells." (PMID 28968989, 2017). "We sought to examine occupational disparities in tumor grade and cytosolic expression of high‐mobility group box‐1 (HMGB1) among renal cell cancer (RCC) patients." (PMID 35712799, 2022). "Therefore, it could be deduced that HMGB1 could realize renal cell carcinoma immune escape by inducing the proliferation and differentiation of MDSCs." (PMID 28968989, 2017). "Therefore, we further investigated whether HMGB1 could promote renal cell carcinoma by enhancing the proliferation of MDSCs." (PMID 28968989, 2017). "Thus, HMGB1 might promote renal cell carcinoma mainly via MDSC." (PMID 28968989, 2017).
Sjögren syndrome (9 papers, 2016 to 2023). "Extracellular high mobility group box 1 (HMGB1) acts as a damage associated molecular pattern molecule through the Toll-like receptor to promote autoreactive B cell activation, which may be involved in the pathogenesis of Sjӧgren’s syndrome." (PMID 28837629, 2017). "In another study, serum HMGB1 and sRAGE were elevated and associated with the EULAR Sjögren’s Syndrome Disease Activity Index (ESSDAI) in patients with SS, and HMGB1 levels were much higher in patients with extra-glandular involvement." (PMID 35250993, 2022). "It is plausible to assume that extracellular HMGB1 acts as an inflammatory cytokine through TLR9 signaling on B cells in this mouse model of Sjӧgren’s syndrome." (PMID 28837629, 2017). "The aim of this study was to investigate the effect of subconjunctival administration of anti-HMGB1 on dry eye in a mouse model of Sjӧgren’s syndrome." (PMID 28837629, 2017). "Moreover, HMGB1 decreased Aqp5 mRNA levels in a mouse model of Sjögren’s syndrome through the activation of the toll-like receptor 4 (TLR4)/NFkB pathway." (PMID 36768212, 2023). "In a mouse model of Sjögren’s syndrome, HMGB1 inhibition restored saliva and tear secretion, suggesting HMGB1 inhibition may represent a new therapeutic strategy for treating the disease." (PMID 36768212, 2023). "HMGB1 has been involved in Sjögren’s syndrome pathogenesis." (PMID 36768212, 2023). "We hypothesize that extracellular HMGB1 in Sjӧgren’s syndrome may trigger strong auto-inflammatory cycles by activating an adaptive immune response and may establish a continuous pathological condition." (PMID 28837629, 2017). "An increased amount of HMGB1 has also been observed in the salivary glands of patients with Sjogren’s syndrome, and HMGB1 may act together with IL-1β and TNF-α in forming a feed-forward loop promoting inflammation." (PMID 28765610, 2017). "Extracellular HMGB1, which is passively released from necrotic cells or actively secreted by macrophages and dendritic cells, is a crucial cytokine that mediates the response to infection, injury, and inflammation, including autoimmune diseases such as Sjӧgren’s syndrome." (PMID 28837629, 2017). "In Sjӧgren’s syndrome, the conjunctival, corneal, and lacrimal epithelial cells are damaged during inflammation, and some of them may undergo necrosis to release extracellular HMGB1." (PMID 28837629, 2017).